SIGLEC14 (sialic acid binding Ig like lectin 14)
Description:
Putative adhesion molecule. Sialic acid-binding paired receptor which may activate associated receptors.
Tractability: Antibody: UniProt places it where antibodies can reach, with high confidence; its Gene Ontology location is reachable by antibodies, with high confidence; UniProt predicts a signal peptide or a membrane-spanning region. PROTAC: its protein half-life has been measured.
Target class: Adhesion
Gene: Protein-coding gene on chromosome 19 (51,639,478 to 51,646,825, reverse strand). Ensembl gene ENSG00000254415.
Subcellular location: Cell membrane
Subcellular location (Human Protein Atlas): Vesicles; Plasma membrane
Pathways (Reactome):
Immune System: DAP12 interactions; Neutrophil degranulation
Gene Ontology:
Molecular function: protein binding; sialic acid binding
Biological process: cell adhesion
Cellular component: plasma membrane; ficolin-1-rich granule membrane; tertiary granule membrane
Genetic constraint (gnomAD): Loss-of-function variants: 10 observed, 21.48 expected, observed/expected ratio (o/e) 0.47, 90% interval 0.29 to 0.79. The synonymous counts are far from expectation, so gnomAD's model fits this gene poorly and the ratio says little. Missense variants: 193 observed, 282.77 expected, observed/expected ratio (o/e) 0.68, 90% interval 0.61 to 0.77. Synonymous variants: 88 observed, 116.74 expected, observed/expected ratio (o/e) 0.75, 90% interval 0.63 to 0.9.
Homologues: Orthologues: chimpanzee SIGLEC14 (82% identical), macaque SIGLEC5 (70% identical), tropical clawed frog siglecl1 (28% identical), tropical clawed frog siglecl2 (28% identical), tropical clawed frog siglecl2 (25% identical), tropical clawed frog siglecl1 (21% identical). Paralogues in human: SIGLEC5 (77% identical), SIGLEC8 (49% identical), SIGLEC9 (48% identical), SIGLEC7 (48% identical), SIGLEC12 (47% identical), SIGLEC10 (47% identical), SIGLEC6 (46% identical), SIGLEC11 (45% identical), CD33 (37% identical), SIGLEC1 (25% identical), MAG (24% identical), SIGLEC16 (24% identical), and 4 more.
Diseases named in the same sentence as SIGLEC14 in open-access papers:
SIGLEC14 is named in the same sentence as 31 diseases in open-access papers, as found by Europe PMC text mining. Sharing a sentence is not in itself a finding about the gene and the disease. The quoted sentences say what the papers report.
chronic obstructive pulmonary disease (4 papers, 2014 to 2021). A chronic and progressive lung disorder characterized by the loss of elasticity of the bronchial tree and the air sacs, destruction of the air sacs wall, thickening of the bronchial wall, and mucous accumulation in the bronchial tree. "The loss of SIGLEC14 caused by SIGLEC14-null allele homozygosity is related to a reduced risk of chronic obstructive pulmonary disease exacerbation." (PMID 33796453, 2021). "The clinical observation of patients with chronic obstructive pulmonary disease (COPD) has shown that the loss of Siglec-14 reduces the risk of COPD exacerbations related to bacterial infections." (PMID 32575400, 2020). "Chronic obstructive pulmonary disease (COPD) patients who do not have Siglec‐14 (a myeloid cell protein that triggers inflammatory responses) are less prone to exacerbation of the disease." (PMID 24994897, 2014).
Alzheimer disease (3 papers, 2021 to 2024). A progressive, neurodegenerative disease characterized by loss of function and death of nerve cells in several areas of the brain leading to loss of cognitive function such as memory and language. "The sialic acid–Siglec interaction systems prevent the excessive and detrimental immune responses, yet the malfunction of interaction with Siglec3/CD33, Siglec-11, and Siglec-14 have been associated with neurodegenerative diseases such as Alzheimer’s disease (AD)." (PMID 39596031, 2024). "Genetic variants of SIGLEC3/CD33, SIGLEC11, and SIGLEC14 have been associated with neurodegenerative diseases such as Alzheimer’s disease, while sialyltransferase ST8SIA2 and SIGLEC4/MAG have been linked to psychiatric diseases such as schizophrenia, bipolar disorders, and autism spectrum disorders." (PMID 38529039, 2024).
breast carcinoma (2 papers, 2023 to 2025). "Here, we analysed the effect of TMX on the binding of soluble recombinant Fc chimeric proteins of inhibitory Siglec-5 and stimulatory Siglec-14 in human breast cancer cell lines." (PMID 36982588, 2023). "Indeed, Siglec-5 was recently characterized as an inhibitor of T cell activation, and combining its targeting with Siglec-14 and Tamoxifen hormone therapy was suggested to enhance anti-tumor immunity in an in vitro breast cancer model." (PMID 40547037, 2025). "Additionally, exposure to tamoxifen increased the binding of Siglec-5 and Siglec-14 fusion proteins to breast cancer cells; however, these effects appeared to be unassociated with oestrogen dependency." (PMID 36982588, 2023).
Sepsis (2 papers, 2017 to 2023). Sepsis is defined as life-threatening organ dysfunction caused by a dysregulated host response to infection. "Siglec-1, Siglec-5, and Siglec-14 play bidirectional roles in sepsis through modulation of inflammation and immunity." (PMID 29209331, 2017).
age-related macular degeneration (1 paper, 2024). Age-related loss of vision in the central portion of the retina (macula), secondary to retinal degeneration. "Five of these proteins (protein-coding genes ECI1, LCT, and NPTXR for glaucoma, WARS1 for age-related macular degeneration (AMD), and SIGLEC14 for diabetic retinopathy (DR)) are newly reported." (PMID 39408566, 2024).
autoimmune disease (1 paper, 2021). A disorder resulting from loss of function or tissue destruction of an organ or multiple organs, arising from humoral or cellular immune responses of the individual to their own tissue constituents. "We plan to analyse a possible involvement of Siglec-14 on human autoimmune diseases in the future." (PMID 34497606, 2021).
gastric cancer (1 paper, 2022). A primary or metastatic malignant neoplasm involving the stomach. "Four distributed genes ACOT1, GSTM1, SIGLEC14, and UGT2B17 showed extremely high frequencies of absence in the gastric cancer population." (PMID 36109518, 2022). "Genes ACOT1, GSTM1, SIGLEC14, and UGT2B17 are highly absent in Chinese Hans, even in the Asian population, compared to the non-Asian healthy population, suggesting a potential association for the high incidence of gastric cancer in the Asian population." (PMID 36109518, 2022). "Genes ACOT1, GSTM1, SIGLEC14 and UGT2B17 are identified as highly absent genes in gastric cancer population." (PMID 36109518, 2022).
glaucoma (1 paper, 2024). Increased pressure in the eyeball due to obstruction of the outflow of aqueous humor. "A total of 11 unique protein-coding genes posterior probability (PP) of H4 > 0.70 finally remained, including GSTM3 for senile cataract, WARS1, C3, IGFBP7, and PILRA for AMD, ECI1, LCT, and NPTXR for glaucoma, EFEMP1 for myopia, and SIRPG and SIGLEC14 for DR." (PMID 39408566, 2024).
glioma (1 paper, 2021). A benign or malignant brain and spinal cord tumor that arises from glial cells (astrocytes, oligodendrocytes, ependymal cells). "In THP-1 cells grown in the presence of U87MG glioma, the exposure to Dex or TMZ caused decreased SIGLEC5 transcripts levels, but increased expression of SIGLEC14." (PMID 33670244, 2021).
gonococcal infection (1 paper, 2019). "The engagement of activating Siglec receptors, such as Siglec‐14 and Siglec‐16, leads to an activation of the pro‐inflammatory signaling cascade that facilitates clearance of gonococcal infection." (PMID 30697344, 2019). "On the other hand, engagement of activating Siglecs, such as Siglec‐14, can contribute to the pro‐inflammatory response that could help clear gonococcal infection." (PMID 30697344, 2019).
hepatocellular carcinoma (1 paper, 2025). A malignant tumor that arises from hepatocytes. "In hepatocellular carcinoma, the expression levels and functions of Siglec-5 and Siglec-14 are closely linked to tumor progression and immune evasion." (PMID 40858654, 2025). "There is a balance between Siglec-5 and Siglec-14; when Siglec-5 activity is enhanced, Siglec-14 activity is reduced, thus promoting hepatocellular carcinoma progression." (PMID 40858654, 2025). "We hypothesize that the interaction between Siglec-14 and Siglec-5 forms a key regulatory axis that can regulate the progression of hepatocellular carcinoma." (PMID 40858654, 2025). "Particularly in hepatocellular carcinoma, the Siglec-14/SYK signaling pathway may participate in the progression of hepatocellular carcinoma by modulating inflammatory responses and the immune microenvironment." (PMID 40858654, 2025). "The interactions among Siglec-5, Siglec-14, SIRPα, SHP1, SHP2, SYK, and ROS create a complex regulatory network in hepatocellular carcinoma." (PMID 40858654, 2025).
joint disease (1 paper, 2019). "Biological inference prioritized notable DMRs associated with skin disease (SIGLEC14, JAM3, PCOLCE, RXRB), skin and/or joint disease (MBP, OSBPL5, SNORD115, HCG26), and joint disease (IL22, ELF5, PPP2R2D, PTPRN2, HCG26)." (PMID 30779748, 2019). "Although few DMRs exceeded a 10% change in methylation, it is noteworthy that many of those which did play roles in the pathogenesis of skin disease (SIGLEC14, JAM3, PCOLCE, RXRB, ELF5, IL22), joint disease (MBP, HCG26, IL22, PPP2R2D, PTPRN2) or are known to be imprinted (OSBPL5, SNORD115)." (PMID 30779748, 2019).
leukemia (1 paper, 2021). A malignant (clonal) hematologic disorder, involving hematopoietic stem cells and characterized by the presence of primitive or atypical myeloid or lymphoid cells in the bone marrow and the blood. "Like sSiglec-5, soluble Siglec-14 derived from mRNA splicing is detected in the blood and suppressed pro-inflammatory responses of membrane-bound Siglec-14+ THP-1 leukemia cell lines." (PMID 34827170, 2021).
meningococcal infection (1 paper, 2024). Infections with bacteria of the species neisseria meningitidis. "Taken together, Siglec-5 and Siglec-14 satisfy all features of NadA receptors suggesting a possible role of NadA in the acute meningococcal infection." (PMID 39041817, 2024).
ovarian carcinoma (1 paper, 2023). A malignant neoplasm originating from the surface ovarian epithelium. "Compared with other SGILEC family proteins, the prognostic role of SIGLEC14 in ovarian cancer is not fully understood." (PMID 36669591, 2023).
periodontitis (1 paper, 2022). An acute or chronic inflammatory process that affects the tissues that surround and support the teeth. "Interestingly, EZH1 and MRPS23 were newly identified, whereas previous studies have verified SIGLEC14 and SIGLEC5 as genetic risk factors for periodontitis." (PMID 36611863, 2022). "Finally, we identified two previously reported genes (SIGLEC5, SIGLEC14) and two novel genes (EZH1, MRPS23), proving that TWAS is a supplemental strategy for studying periodontitis’ etiology." (PMID 36611863, 2022).
psoriasis (1 paper, 2026). An autoimmune condition characterized by red, well-delineated plaques with silvery scales that are usually on the extensor surfaces and scalp. "Serum tumor necrosis factor alpha (TNF-α), interleukin 1-beta (IL-1β), high-sensitivity C-reactive protein (Hs-CRP), sialic acid, and Sialic acid binding Ig-like Lectin-14 (Siglec-14) levels were investigated in controls and psoriasis patients." (PMID 41598424, 2026).
tuberculosis (1 paper, 2022). A chronic, recurrent infection caused by the bacterium Mycobacterium tuberculosis. "Due to the Siglec-14–null polymorphism, Siglec-14 is absent in some humans, a condition that is associated with M. tuberculosis growth in monocytes and susceptibility to TB." (PMID 36509283, 2022). "Our current findings further demonstrate that Siglec-14 plays an important role in restricting M. tuberculosis growth in human MDMs and plays an important role in innate protective immune responses in nonconverter HHCs of patients with TB." (PMID 36509283, 2022).
tumor (9 papers, 2018 to 2025). "In tumor-associated macrophages (TAMs), Siglec-5 associates with the tyrosine phosphatases SHP-1 and SHP-2 to transmit inhibitory signals, while Siglec-14 interacts with the adapter protein tyrosine kinase SYK to convey activating signals." (PMID 40858654, 2025). "Specifically, increased ROS production under hypoxia conditions activates HSF1 and HSP70, promoting the expression of Siglec-5 and Siglec-14, which in turn affects immune cell functions and tumor progression." (PMID 40858654, 2025). "Research has shown that Siglec-14 can modulate immune cell functions through interactions with its ligands, thereby affecting the tumor immune microenvironment." (PMID 40858654, 2025). "It has been shown that expression levels of CD33-related Siglecs are upregulated in tumor-infiltrating T cells in different human carcinomas and the upregulation of Siglec-14 on monocyte has been observed in SLE patients." (PMID 30294327, 2018). "The interactions and expression changes between Siglec-5 and Siglec-14 not only affect immune cell function, but may also influence tumor progression." (PMID 40858654, 2025). "Because SIGLEC14 is an innate immune cell activation receptor, the integrity of the SIGLEC14 gene provides a molecular basis for ensuring the M1 polarization of macrophages or tumor-arresting polarization of neutrophils." (PMID 37133224, 2023). "Siglec-14 regulates immune cell activity through interactions with SYK, thereby influencing tumor progression." (PMID 40858654, 2025).
cancer (4 papers, 2018 to 2023). A tumor composed of atypical neoplastic, often pleomorphic cells that invade other tissues. "Hitherto, the correlation of SIGLEC14 null variation with cancer has not been reported yet." (PMID 36109518, 2022).
infection (3 papers, 2019 to 2025). The state of being infected such as from the introduction of a foreign agent such as serum, vaccine, antigenic substance or organism. "In fact, Siglec‐14 has been shown to counteract the exploitation of Siglec‐5 by GBS, and Siglec‐16 reduces survival of E. coli K1 during infection." (PMID 30697344, 2019).
SIGLEC14 also shares sentences with these, for which no sentence is quoted: autism spectrum disorder (1 paper); bipolar disorder (1); breast tumor (1); bronchopulmonary dysplasia (1); diabetic retinopathy (1); myopia (1); neurodegenerative disease (1); psychiatric diseases (1); sarcopenia (1); schizophrenia (1).